GLUL (glutamate-ammonia ligase)
Diseases named in the same sentence as GLUL in open-access papers (continued):
Sharing a sentence is not in itself a finding about the gene and the disease.
preeclampsia (1 paper, 2025). Preeclampsia is a hypertensive disorder of pregnancy that is characterized by new-onset hypertension with proteinuria presenting after 20 weeks of gestation, and depending on mild or severe forms may initially present with severe headache, visual disturbances, and hyperreflexia. "qRT-PCR confirmed that GLUL and NCL expression decreased and DDX28 and RIOK1 expression increased in clinical placental samples of preeclampsia group." (PMID 40552285, 2025).
prion disease (1 paper, 2024). A transmissible disease that is caused by a protein that is able to induce abnormal folding of normal cellular proteins, leading to characteristic spongiform brain changes, which are associated with neuronal loss without an inflammatory response. "Therefore, the specific association between GLUL upregulation and prion diseases suggests a unique interplay between glutamine/glutamate metabolism and disease progression, setting PrDs apart from other NDDs." (PMID 39259763, 2024). "Again, GLUL protein levels were unaltered in AD, DLB and FTD, highlighting its distinct role in prion diseases compared to other neurodegenerative conditions." (PMID 39259763, 2024). "However, it is important to note that while GLUL expression was downregulated in ALS, it was upregulated in prion diseases." (PMID 39259763, 2024).
renal carcinoma (1 paper, 2014). A carcinoma arising from the epithelium of the renal parenchyma or the renal pelvis. "Using previously published datasets characterizing gene expression in prostate and renal cancers, a potentially deleterious effect of GAD1 overexpression and GLUL underexpression on patient survival was identified." (PMID 24551133, 2014).
retinal detachment (1 paper, 2011). An eye emergency condition which may lead to blindness if left untreated. "For example, retinal detachment upregulates GFAP expression and concomitantly results in loss of GLUL expression and extensive derangement of glial and neuronal metabolite profiles." (PMID 21985191, 2011).
sporadic Creutzfeldt-Jakob disease (1 paper, 2024). A rare sporadic human prion disease characterized by rapidly progressive cognitive impairment in combination with variable neurologic signs and symptoms including myoclonus, visual or cerebellar problems, pyramidal or extrapyramidal features, or akinetic mutism. "The glutamate-ammonia ligase (GLUL) gene exhibited uniform upregulation in skeletal muscles of mice infected with three distinct scrapie prion strains (RML, ME7, and 22L) and in victims of human sporadic Creutzfeldt-Jakob disease." (PMID 39259763, 2024).
tumor (114 papers, 2010 to 2026). "GLUL, an enzyme involved in glutamine metabolism, has been linked to autophagy regulation and tumor cell survival." (PMID 40281780, 2025). "Most enzymes were significantly associated with luminal A tumours (P < 0.05), the only subtype that was positively associated with glutamine synthetase enzyme (GLUL) (P < 0.05)." (PMID 39843491, 2025). "Additionally, GLUL plays an important role not only in cancer cells but also in cells in the tumor microenvironment (TME), including cancer-associated fibroblasts (CAFs) and macrophages, where GLUL expression is also higher." (PMID 39519347, 2024). "Importantly, high levels of cytoplasmic GPER, GLUL, and glutamine production in CAFs were associated with adverse pathological characteristics of tumours, such as large tumour size, high TNM stage, poor histology grade, and reduced survival." (PMID 39690134, 2024). "Unexpectedly, this subset was deficient in tumor samples compared to paratumor samples, indicating that GLUL-SQSTM1- RTM may act as a positive regulator of immunity." (PMID 38149248, 2023). "Examination of dabrafenib-treated BrafV600E/+;Rnf43fl/fl;Znrf3fl/fl lesions revealed a reduction in proliferation, mTOR signalling and tumour growth along with an upregulation of GLUL and a decrease in CDH1 and SOX9 levels." (PMID 41261129, 2026). "Collectively, our findings demonstrated that in tumor cell glutamine metabolism, the GLUL-mediated FGF17/FGFR4/MEK5/ERK5 signaling axis sustains redox homeostasis in the tumor microenvironment via activation of NRF2-dependent antioxidant programs." (PMID 41551579, 2025). "GLUL, overexpressed in pancreatic and liver cancers due to c-Myc driven promoter demethylation, supports tumor growth." (PMID 41179661, 2025). "Conversely, other literature indicates that silencing GLUL expression inhibits nucleotide synthesis, suppresses tumor growth in LSL-KrasG12D/+; Pdx1-Cre (KPC) PDAC mice, and increases survival rates." (PMID 39519347, 2024). "Collectively, these data demonstrate that GPER mediates glutamine biosynthesis and secretion in CAFs co‐cultured with TNBC cells by regulating GLUL expression and enhances glutamine uptake in tumour cells by regulating LDHB expression." (PMID 39690134, 2024). "Given the prevalence of GLUL+SQSTM1+RTM cells in PDAC tumor tissues, and their interaction with CD8+T cells revealed by the cell chat analysis, it becomes apparent that a deeper exploration is warranted." (PMID 38149248, 2023). "GLUL catalyzes the metabolism of glutamate to glutamine and is highly expressed in tumor tissue, lymphoid tissue and muscularis mucosa (Fig. 3a3, b1)." (PMID 37164975, 2023). "GLUL expression in macrophages was positively correlated with anti‐inflammatory score and was higher in high‐grade and invasive tumor samples." (PMID 36587392, 2023). "According to our knowledge, these data are the first to reveal the relationship between GLUL expression and subtypes of tumor-infiltrating immune cells." (PMID 36619229, 2023). "HepG2 has a large in-frame deletion in the CTNNB1 gene comprising 116 codons of exons 3 and 4 and a mutation of the TERT promoter and represents the fetal tumor subtype with high GLUL expression and GS abundance." (PMID 34235580, 2021). "In the circulation asparagine helps circulating tumor cells survive shear and oxidative stress whilst at a distinct metastatic sites, asparagine facilitates cell growth and survival by inducing glutamine synthetase (GLUL) expression and glutamine biosynthesis." (PMID 33339340, 2020). "More recent studies on amino acids in the tumor microenvironment have demonstrated that glutamine can be obtained by cancer cells from the tumor microenvironment by increasing the activity of glutamate ammonia ligase, a key enzyme in glutamine synthesis." (PMID 31500658, 2019). "Immunostaining of histological sections also showed that resibufogenin stimulated the expression of RIP3, PYGL, GLUD1 and GLUL in the tumor tissues." (PMID 30029665, 2018).
tumor (continued). "Collectively, these results confirmed that glutamine metabolism in NSCLC activates the FGF17/MEK5/ERK5/NRF2 signaling pathway via GLUL, thereby lowering oxidative stress levels in the tumor microenvironment and enhancing migratory and invasive capacities of tumor cells." (PMID 41551579, 2025). "Conversely, GLUL expression in tumour cells remained unchanged." (PMID 39690134, 2024). "In addition, pericentral hepatic markers and WNT target genes, such as CYP2E1 and GLUL, were broadly expressed in the tumor region, contrasting with the zonated pattern in the normal tissue." (PMID 39567475, 2024). "GLUL has been identified to participate in carcinogenesis and tumor progression." (PMID 35756672, 2022). "Here, we found that GLUL was involved in OIP5-AS1-mediated tumor promotion in NPC cells." (PMID 35756672, 2022). "In contrast, luminal tumor cells express GLUL and are resistant to glutamine deprivation." (PMID 34631530, 2021). "In contrast, positive correlation between SLC7A5 and the glutamine synthase enzyme GLUL was observed in luminal A tumours, suggesting that this subtype might rely on glutamine neosynthesis rather than uptake." (PMID 29566741, 2018). "Eight genes were downregulated after S6K1 silencing, but upregulated after S6K2 knock-down, among these the EGFR ligand amphiregulin (AREG), the glutamate-ammonia ligase (GLUL) involved in glutamine synthesis, and the CDK5 and ABL1 enzyme substrate 1 (CABLES1), implicated as a tumour suppressor." (PMID 26698305, 2015). "In addition, genetic deletion of GLUL inhibits tumor metastasis in a process characterized by increased tumor vessel pruning and inhibition of seeding of metastatic lung tumors, suggesting a critical role for glutamine metabolism in immune suppression and tumor metastasis." (PMID 38701369, 2024). "The resulting Lgr5+ hepatocyte-derived BrafV600E-driven tumours expressed the zone 1 marker CDH1 and had reduced expression of the zone 3 and WNT marker GLUL." (PMID 41261129, 2026). "Increased GLUL expression was found in TAM and Mono 3 clusters in the tumor BM relative to the distal, benign, and involved fractions." (PMID 38701369, 2024). "The result showed that the gene expression of SLC3A1 and GLUL were highly expressed in Macro_APOE/CTSZ compared with other cell types in CRC and LC, and were upregulated in macrophage derived from tumor than normal tissues in CRC." (PMID 36587392, 2023). "Although GLUL-SQSMT1- RTM was specifically present in PDAC tumor tissues, it was noteworthy that the majority of RTM in the TME are characterized by the expression of GLUL and SQSTM1." (PMID 38149248, 2023). "Glutamate‐to‐glutamine metabolic pathway and GLUL expression, specifically activated and overexpressed in Macro_APOE/CTSZ, were higher in high‐grade compared with low‐grade tumor samples." (PMID 36587392, 2023). "A differential abundance analysis between proteomes of NK cells isolated from liver and tumor tissues identified four proteins that were increased in tumor NK cells (Log2 fold change > 2; p value < 0.01): AKR1B10, GLUL, IGHMBP2, and AFAP1L2." (PMID 37388918, 2023). "Tumor cells from patient #4001 were characterized by overexpression of AFP, GPC3, DUSP9, DLK1, GLUL, and AXIN2, a marker of Wnt/β-catenin pathway activation." (PMID 37932266, 2023). "In macrophages from tumor samples, two NPA genes, GLUL and SQSTM1, were found to be up-regulated, while SLC25A6 exhibited down-regulation." (PMID 38149248, 2023). "Another cluster of special interest is the GLUL-SQSTM1- RTM subpopulation, which is enriched in PDAC tumor tissues and acts as a positive regulator of immunity." (PMID 38149248, 2023). "Tumours that have a more luminal and hormone‐receptor positive phenotype could overcome this vulnerability by expressing genes that provide glutamine as product (Glutamine synthase, GS; GLUL) and therefore balance the metabolic flux between glycolysis and glutaminolysis." (PMID 35962472, 2022).
tumor (continued). "Data of expression databases revealed that GLUL and ASNS are overexpressed in HB compared to non-tumor liver tissue." (PMID 34235580, 2021). "In contrast, HUH7 cells showed a higher expression of 98 metabolic targets upregulated in tumours (e.g. HK2, PKM, PSPH, GLUL, ASNS, and fatty acid synthesis enzymes ACLY, FASN)." (PMID 30176945, 2018). "These in vivo data suggested that resibufogenin inhibits tumor growth through inducing RIP3-mediated activation of PYGL, GLUD1 and GLUL to induce necroptosis in CRC cells." (PMID 30029665, 2018). "The expression level of CTLA4 only correlated with central tendency parameters, while expression of GLUL, FGFR4, tumour stemness markers KRT19 and EPCAM and immune checkpoint PDCD1 showed significant correlations with MRI heterogeneity parameters only." (PMID 28550313, 2017). "However, the specific regulatory mechanism of tumour glutamine metabolism through the stromal GLUL in the TNBC microenvironment, especially the close relationship among GPER, GLUL, and CAFs, still demands further exploration." (PMID 39690134, 2024). "Notably, blocking glutamine metabolic coupling by knocking down GPER and/or GLUL in CAFs resulted in reduced glutamine production and decreased expression of ASCT2 and GLS1 in tumours." (PMID 39690134, 2024). "Specifically, a group of 40 well-defined genes, classified according to their function, were able to distinguish between 2 different GBM signatures revealing the possible different proliferative potential in high grade GBM tumours (VIM, GLUL, PLK1, HUWE1, RPS4X...)." (PMID 20735813, 2010). "The analysis showed that GLUL expression level negatively correlates with tumor purity, suggesting that tumor cells are not a major contributor to GLUL expression variations and, more importantly, that cells other than tumor cells contribute to GLUL expression." (PMID 34260142, 2021). "Critically, differentiation to an Lgr5+GLUL+ zone 3 fate, which is not permissive to oncogenesis, needs to be reversed for WNT-mutant clones to progress to early tumours." (PMID 41261129, 2026). "The tumours that arose in this genetic background had low WNT pathway activation, did not express nuclear Ctnnb1 and GLUL, and expressed IGFBP2 at variable levels." (PMID 41261129, 2026).
cancer (77 papers, 2011 to 2025). A tumor composed of atypical neoplastic, often pleomorphic cells that invade other tissues. "GLUL encodes glutamine synthetase, which supports cancer cell proliferation by promoting glutamine metabolism." (PMID 38872167, 2024). "Finally, cancer cells can synthetize glutamine de novo in an ATP-dependent reaction catalyzed by glutamine synthetase (GS; glutamate-ammonia ligase, encoded by GLUL gene), which drives condensation of glutamate and ammonia in the cytosol." (PMID 36768660, 2023). "Thus, mutations leading to reduced GLUL transcription should provide a survival advantage for cancer cells." (PMID 31817360, 2019). "Conversely, GLUL stabilises N-calmodulin by antagonising β-catenin, thereby impeding cancer invasion and metastasis." (PMID 40598593, 2025). "In various types of cancers, it enhances the glutamate‐ammonia ligase (GLUL) expression level, which is involved in the fresh synthesis of glutamine." (PMID 40567251, 2025). "Recent findings have indicated that levels of the atypical methyltransferase METTL1 are elevated in cancer cells, thereby promoting glutamine synthase (GLUL) expression in an m6A-dependent manner, which in turn facilitates cancer cell proliferation." (PMID 40598593, 2025). "We also investigated GLUL expression in various other types of cancer via the TCGA database and Human Protein Atlas databases." (PMID 36619229, 2023). "When extracellular glutamine is scarce, cancer cells can increase their production through the enzyme glutamate-ammonia ligase (GLUL)." (PMID 35745875, 2022). "GLUL is involved in tumorigenesis in a variety of cancers; however, the function of GLUL in NPC is unclear." (PMID 35756672, 2022). "It has been described that hypoxia enhances glutamine synthesis and uptake in cancer cells by increasing glutamine synthetase (GS, also known as GLUL) and the number of glutamine transporters such as SLC38A2." (PMID 35408935, 2022). "Even though mammalian cells are capable of glutamine production due to the activity of glutamine synthetase (GLUL), some cancer cells require exogenous glutamine, which is catabolized in the mitochondria by another enzyme—glutaminase (GLS)." (PMID 35409206, 2022). "Glutamine dependency is considered to be enhanced in cancer cells, and increased glutamine catabolism in MYC-induced liver tumors is associated with GLUL downregulation." (PMID 34696350, 2021). "In support of this statement, application of a single‐cell signature matrix from GSE146026 RNA sequencing data to the same TCGA dataset revealed in grade 3 patients a strong upregulation of GLUL expression in TAMs compared with cancer cells." (PMID 34260142, 2021). "A study reported that high expression of GLUL affects cellular response to irradiation in radiation-resistant cells and facilitates growth of cancer cells." (PMID 33173435, 2020). "Here, we showed that GLUL ablation induced resistance to several different cancer drugs in specific cell lines." (PMID 31817360, 2019). "Here, we demonstrated that pharmacological inhibition of the malate-aspartate shuttle reduced viability in resistant GLUL KO A549 cells compared to control cells, thus connecting malate-aspartate metabolism with drug tolerance in cancer cells." (PMID 31817360, 2019). "This suggested that the ability of GLUL KO to confer drug resistance was confined to specific cancer cell types." (PMID 31817360, 2019). "Flag-GLUL re-sensitized A549-KO cells to docetaxel, confirming that GLUL expression influenced drug responsiveness in a specific cancer cell type." (PMID 31817360, 2019). "Given the well-recognized glutamine dependency of many cancer cells, we investigated the roles of GLUL and GLS2 in the relative glutamine independence of the luminal-type cells." (PMID 21852960, 2011). "The expression level of GLUL was found to be significantly lower in cancer tissues." (PMID 40598593, 2025).